CD4 (CD4 molecule)
Diseases named in the same sentence as CD4 in open-access papers (continued):
Sharing a sentence is not in itself a finding about the gene and the disease.
tumor (continued). "According to these series of theories, we previously reported that CD20+ TILs may support an increase in CD4+ and CD8+ TILs, altering the anti-tumor response and resulting in a positive prognosis in TNBC." (PMID 34089486, 2021). "To test whether the colocalisation pattern in adjacent DCIS differs according to T cell subsets, we evaluated the quantitative number, ratio and DCIS immune colocalisation using CD4, CD8 and FOXP3 cells in the IHC dataset of adjacent tumours." (PMID 33649333, 2021). "Altogether, tumor growth inhibition after PD-1 blockade was due to the expansion of CD8+ T cells expressing the costimulatory molecule ICOS and a concomitant reduction in the frequency of CD4+Foxp3+ regulatory T cells." (PMID 34912335, 2021). "Taken together, our findings reveal that BATF overexpression bypasses the need for CD4+ T cell help and could be harnessed to provide therapeutic benefits by enhancing effector CD8+ T cell survival and anti-tumor functions." (PMID 33809259, 2021). "Resected tumor tissue from five patients showed CD4+ and CD8+ infiltration that was not present in historical controls and overlapped with viral RNA detection." (PMID 33535555, 2021). "The partial correlation between the SAMD9 expression level and the six immune cell types: B cell, CD4 T cell, CD8 T cell, neutrophils, macrophages and dendritic cells in the tumor microenvironment was systematically estimated based on the Tumor Immune Estimation Resource (TIMER) algorithm." (PMID 33936093, 2021). "We applied three different panels to demonstrate the levels of VISTA in tumor-infiltrating CD68+ macrophages, CD3+ T cells, CD19+ B cells, CD4+ T-helper cells, and CD8+ cytotoxic T cells, as well as to explore the association between VISTA expression and PD-1/PD-L1." (PMID 33237432, 2021). "Different preclinical studies reported that PARP inhibitors significantly increased tumor infiltrating CD4+/CD8+ T cells which were activated by the stimulator of interferon genes (STING) pathway and recruited to tumors by tumor-specific neoantigens when combined with ICIs." (PMID 33740125, 2021). "Besides gene expression-based analyses, we also performed immunohistochemistry (IHC) with our 9 SCLC tumor samples to quantify tumor-infiltrating CD8+ and CD4+ T cells." (PMID 33750914, 2021). "If there is consistency in the literature regarding CD8+ lymphocyte tumor infiltration in most cancers, the results reported until now for CD4+ lymphocytes are far from being clarified." (PMID 34066837, 2021). "High salt treated CD4+T cells obtained from all three sources (DLNs, tumor-splenocytes and non-tumor splenocytes) demonstrated significant anti-tumor efficiency compared with the respective mannitol treated CD4+T cells." (PMID 33918403, 2021). "B lymphocytes are assumed to bind tumor antigens through surface immunoglobulin (Ig) molecules, process them, and then present tumor-derived antigens through major histocompatibility complex classes I and II to induce the activation of both CD8+ cells and CD4+ T lymphocytes." (PMID 33726701, 2021). "It was reported that microvesicles and exosomes released by tumor cells contribute to cancer immunosuppression by inducing, in T-cells, the transition from the effector phenotype (CD4+CD25−) to the regulator (CD4+CD25+Foxp3+) phenotype, its clonal expansion, and activation." (PMID 33671415, 2021). "In this altered cytokine milieu, CD4+ T cells do not differentiate into effector T cells but instead differentiate into peripheral Treg cells that restrain anti-tumour immunity." (PMID 34439160, 2021). "Immune-infiltrating cells are an important component of the tumor microenvironment, mainly including B cells, CD4+ T cells, CD8+ T cells, neutrophils, macrophages, and dendritic cells, which have been proven to influence the immunotherapy response and promote tumor progression." (PMID 34326876, 2021).
tumor (continued). "Most importantly, the reduced tumor-infiltrating CD4+ T cell numbers do not result in an altered MC38 tumor growth." (PMID 34248938, 2021). "Having seen slowed tumor growth and increased total and activated CD4+ and CD8+ T cells in tumors in p50(f/f);Lys‐Cre mice, we sought to determine whether depletion of CD4+ or CD8+ T cells would accelerate tumor growth." (PMID 33480449, 2021). "Interestingly, CA170 significantly increased tumor-infiltrating CD8+ T cells, and enhanced effector-memory T cell frequencies and function for both CD4+ and CD8+T cells." (PMID 34302042, 2021). "The density of exhausted BTLA+ CD4+ T cells around malignant CD4+TOX+ cells was higher in tumors than it was in plaques, suggesting that undesired safeguards are in place within the tumor microenvironment that prevent immune activation and subsequent cancer eradication." (PMID 34885092, 2021). "However, both AURKA and AURKB expression were significantly inversely correlated with markers for T-cell infiltration of the tumor: CD3E, CD4, CD8A, LCK, PDCD1 and IFNG." (PMID 33123754, 2021). "In chronically stressed mice, mitogen-induced T cell proliferation is reduced, the number of CD4+ T lymphocytes is reduced, and tumor necrosis factor (TNF) and interferon production are reduced, promoting tumor proliferation and progression via inhibition of T cell-mediated immunity." (PMID 34988010, 2021). "While this points towards the ambiguity of MHC binding prediction algorithms, this effect is not undesirable because CD4+ T cells have been shown to aid in tumour clearance and similar effects must be investigated in LS/CMMRD vaccination trials as well." (PMID 34067951, 2021). "We observed that the combination therapy led to a reduction in tumor growth, with increased frequencies of CD4+ and CD8+ T cells and no change in Tregs." (PMID 34649584, 2021). "Importantly, daily CR elicits a unique signature of immune activation by significantly reducing the number of tumor-promoting immune cells (CD11b+Gr1+), while upregulating tumor-fighting (CD8+ and CD4+) immune cells in peripheral tissues." (PMID 34707136, 2021). "Tumour neoantigen mimicry by microbial species is therefore likely to produce T cell clones of both the CD8 and CD4 lineage that are tumour-reactive despite never having previously seen actual tumour antigens." (PMID 33824481, 2021). "Later it was shown that CD8+ T cell responses could be raised against malaria antigens, and several studies followed that reported α-GalCer-enhanced CD4+ and CD8+ T cell responses to protein and peptide antigens, including tumour antigens." (PMID 36845569, 2021). "In accordance with scRNA-seq data, the Oxali + anti–PD-L1 combo increased the percentage and/or total numbers of tumor-infiltrating CD8+ and CD4+ T cells, CD107+IFNγ+ CTLs, IFNγ+ CD8+, and TNF+IFNγ+ CD8+ T cells, CD8+CD44+ Teff cells, and CD8+CD44+PD1+TIM-3+ T cells analyzed by flow cytometry." (PMID 33602823, 2021). "The tumor microenvironment (TME) contains a plethora of immune cells (i.e., macrophages, neutrophils, mast cells, eosinophils, CD8+ and CD4+ T cells, etc.)which produce a multitude of mediators that promote cell proliferation, angiogenesis, lymphangiogenesis, and the formation of metastasis." (PMID 34064197, 2021). "The PD-L1 expression in tumor-induced exhausted CD4+ T cells was found to be controlled by the interplay of chromatin remodeling SWI/SNF and PRC2 complexes, suggesting that EZH2 is involved in regulating PD-L1 expression in exhausted CD4+ T cells." (PMID 34737746, 2021). "This was accompanied by an increase in the percentage of tumor‐infiltrating CD4+ T cells, but not B cells, NK cells, NKT cells, or CD8+ T cells." (PMID 34026453, 2021). "BEMPEG favors activation and expansion of T‐effector cells and NK cells, without expansion of unwanted regulatory CD4+ T cells (Treg) in the tumor tissue." (PMID 33152115, 2021).
tumor (continued). "The absence of lymphocytes reduced the overt tumor growth of Mmp2-OE cells and reconstitution with CD4+ T cells (OTII+) partially rescued the phenotype." (PMID 34032639, 2021). "Our results indicated that the intratumoral CXCL13 expression could induce enhanced infiltration of CD4+, CD8+ T lymphocytes, and CD11b+CD11c+ DC in the 4T1 tumor microenvironment." (PMID 35693216, 2021). "Additionally, multiple distinct functional clusters of tumor-specific reactive CD8+ and CD4+ TILs observed in vitro were also present in situ." (PMID 34707600, 2021). "Immunofluorescence-based staining of T-cell subsets in the ilea and tumor beds revealed an inverse correlation between CD3+ and CD4+ T lymphocytes within the ileal epithelium (EP) or lamina propria (LP), and CD8+ tumor-infiltrating lymphocytes (TILs) in the invasive margins of the resected pCC." (PMID 33262469, 2021). "If the balance between the CD4+ and CD8+ is broken, the immunity will be suppressed and the mutated tumor cells will not be recognized." (PMID 34956380, 2021). "Researches have shown that miR155 upregulation promotes the differentiation of naive CD4+ T cells into Th1 cells through the regulation of the IFN-γ signal, which is of great significance for T cells to exert anti-tumor function for the secretion of IFN-γ, TNF-α, IL-2 and other cytokines." (PMID 35046962, 2021). "CD4+ and CD8+ TILs were more prominent in the tumour stroma than in the tumour epithelium." (PMID 33402737, 2021). "A comparison of a panel of adjuvants on antitumor responses upon peptide vaccination in tumor mouse models showed that CPG-ODNs and PolyI:C promoted the expansion of antigen-specific CD8 and CD4 effector T cells compared to QuilA and Imiquimod that decreased the effector T cells." (PMID 34064410, 2021). "Effective tumour eradication requires tumour‐specific CD8 and CD4 T cells." (PMID 33655701, 2021). "Infiltrated CD4+ Tfh cells express CXCL13, which has been speculated to initiate GC formation and enhance TLS development by homing immune cells to peritumoral or tumor sites." (PMID 34947813, 2021). "Our results found that MDSCs (CD11b+Gr1+) and Tregs (CD4+CD25+Foxp3+) were elevated significantly on days 21 and 28 after tumor implantation, indicating that both Tregs and MDSCs might affect host tumor immune response." (PMID 33469123, 2021). "Moreover, we found an increased population of activated CD44+ T cells in tumor and TNF-α producing effector CD4+ and CD8+T cells in the spleen." (PMID 33499256, 2021). "Interestingly, Tim-3 was found to be overexpressed on peripheral CD4+ and CD8+ T-cells in glioma patients and the level of Tim-3 expression in CD8+ T-cells was correlated with tumor grade." (PMID 34771550, 2021). "For instance, our data showed that TGFβ1 gene encoding TGF-β, which is known to inhibit T effector cell functions, promote Treg survival/differentiation, and support tumor invasion and metastasis, was expressed at higher levels on CD8+ TILs compared to CD4+ TILs." (PMID 33916009, 2021). "Tumor-infiltrating lymphocytes (TILs) are important components of the tumors immune microenvironment and play a vital role in the formation and progression of tumor, including CD8+ CTLs, CD4+ Th, CD4+/CD25+/FoxP3+ Treg." (PMID 34094918, 2021). "Importantly, several of our LP-pulsed DC vaccines plus CpG increased CD4+ and CD8+ T cell infiltration, but nonetheless, only slightly delayed tumor growth." (PMID 34771674, 2021). "The TIPs inflamed (tumor, CD8) and inflamed (tumor, CD4) represent patterns where tumor cells and immune cells are co-clustered, whereas the TIPs excluded (tumor, CD8) and excluded (tumor, CD4) represent patterns where immune cells are segregated from tumor cells." (PMID 33791196, 2021). "Effective tumor eradication requires tumor-specific CD8+ and CD4+ T cells." (PMID 34604068, 2021).
tumor (continued). "Comparison of T cell proportions between tumor and MPE in these studies are limited by small sample sizes, and whether proportions of CD4+ and CD8+ T cells are similar in matched tumor and MPE samples are unknown." (PMID 33987104, 2021). "Taken together, adiponectin-expressing tTreg precursors elicit anti-cancer activity at least partly by facilitating T-cell selection in TNC complexes, suppressing the release of immature CD4+CD8+ cells from thymus, and promoting the immune cell recruitment within the tumor microenvironment." (PMID 33727658, 2021). "Tumor slides were immunohistochemically stained for CD3, CD8, CD4, CD20, CD38 and FoxP3." (PMID 33006650, 2021). "Tumor-infiltrating T lymphocytes, particularly the CD4+ and CD8+ T cells, and their immunoregulatory cytokines, representing adaptive immunity, execute key effector cytotoxic functions in the tumor microenvironment and mediate responses to immune checkpoint inhibition." (PMID 34200786, 2021). "In line with the previous results, MIT-high group had higher inflammatory infiltration but tumor-promoting immune environment (e.g., CD8+ T, CD4+ T cells, Tregs, Th2 and M2 macrophages), while MIT-low group exhibited higher stroma infiltrations (e.g., CAFs, Endothelial and Pericytes)." (PMID 35087839, 2021). "Al- though CD4+ T cells generally display minimal in vivo or in vitro lytic activity against tumors, one could say that their activation in the TME determines tumor rejection to a greater extent than activation of CD8+ T cells." (PMID 33669271, 2021). "Notably, in spite of the elevated number of T cell players found in the tumor microenvironment, the most consistent survival predictors are (i) the number of TILs and (ii) the ratio between CD8+ cytotoxic T cells and CD4+ FOXP3+ Tregs." (PMID 34787568, 2021). "Moreover, immunofluorescence analysis of abscopal tumour sections further confirmed that the tumours in the LIA+L group showed significantly increased CD8+ and CD4+ T-cell infiltration compared with the control groups." (PMID 34400628, 2021). "Besides TAMs, T cells including CD4+ T helper cells and CD8+ CTLs have a crucial role in tumor rejection." (PMID 33537094, 2021). "It has been reported that the GBM TME influences the CD4+ TIL’s plasticity, which dictates whether they possess immunotolerant or anti-tumor activity." (PMID 34012510, 2021). "Moreover, IL-10 has pro-tumor activity in TME, and IL-10 facilitated Tregs and M2-like macrophages development, as well as counteracting CD4+ T cells, cytotoxic CD8+ T cells and NKs tumoricidal function." (PMID 33957948, 2021). "The related OR was 0.514 (95% CI: 0.081–0.806), suggesting a decreased risk of death for patients with infiltration of these cells comparatively to those without tumor-infiltrating CD4+ cells." (PMID 34885185, 2021). "Considering that an important percentage of both CD4+ and CD8+ tumor-infiltrating T cells expressed PD-1 in the anti-DEC-205:16E5-treated mice, we tested whether an anti-PD-1 blocking mAb could increase mice survival." (PMID 33717073, 2021). "IL-2 is an important factor for maintenance of CD4+ regulatory T cells, but also plays a critical role in the proliferation and differentiation of CD4+ T cells, promotion of CD8+ T cell and NK cell cytotoxic activity, and modulation of T cell differentiation programs in response to tumor antigens." (PMID 33807849, 2021). "The selective distribution of CB1 and CB2 receptors on different subsets of CD4+ and CD8+ T cells involved in tumor growth is largely unknown." (PMID 34064197, 2021). "In addition, DC pulsed with these ExVs more effectively favored CD4+T cell proliferation and Th1 cytokine secretion, induced anti-leukemic CTL response and inhibited tumor growth." (PMID 33435564, 2021). "A good prognosis was observed in TNBC in which tumors were highly infiltrated by CD20+ TILs combined with CD4+ and CD8+ TILs; therefore, CD20+ TILs may support CD4+ and CD8+ TILs in altering the anti-tumor response." (PMID 33726701, 2021).
tumor (continued). "In parallel, our multiplex immunofluorescent staining also showed a concordant increase in the number of CD4+ and CD8+ T cells per mm2 of tumor section in GBM.pembro patients compared to GBM.rec patients, while the number of CD14+ myelo-monocytic cells was similar." (PMID 34836966, 2021). "Macrophages M1, CD4 T cells, CD8 T cells and γδT cells were both highly presented in the Immunity_H subtype of the two independent datasets which further suggested increased anti-tumor immune activity in the immunity_H subgroup." (PMID 34893046, 2021). "Furthermore, expression levels of CD4, CD66b, and CD166 were positively correlated with US31, suggesting that it was involved in regulating the tumor immune microenvironment of GC." (PMID 33959494, 2021). "The immunohistochemistry revealed that the combination therapy promoted the induction of apoptosis while inhibited the proliferation of tumor cells, which was accompanied by the enhanced infiltration of CD8+ T and CD4+T cells as well as the reduction of M2 macrophages." (PMID 34373258, 2021). "Analysis of the tumor microenvironment by flow cytometry revealed that the primary tumor showed a higher frequency of CD3+ and CD8+ cells, while the proportion of CD4+Foxp3+ cells was not different from the recurrent tumor." (PMID 34221953, 2021). "However, when combined with pectin, anti-PD1 mAb significantly increased the accumulation of CD4+ and CD8+ T cells in the tumor compared with other groups." (PMID 33754054, 2021). "Based on previous studies, CD4+ T cells are related to the production of effective antitumor immune responses, while Treg cells inhibit the antitumor immune microenvironment by secreting cytokines IL10 and TGFβ in the tumor microenvironment." (PMID 34220801, 2021). "Through the TIMER database 48, 49, we explored the BAX may effect tumor-infiltrating immune cells (B cell, CD8+ T cell, CD4+ T cell, macrophage, neutrophil, and dendritic cell)." (PMID 33390811, 2021). "The result of EPIC analysis demonstrated that ACADS expression levels were positively related to CD4+ T cells, which might promote CD8+ T cells activation and induce anti-tumor immune responses." (PMID 34790035, 2021). "Tumor cells were CD3 positive and reactive for both CD4 and CD8." (PMID 34072328, 2021). "In low-risk patients, we identified significantly higher numbers of CD68 +, PD-L1 + CD68 + and PD-L1 + FOXP3 + cells in the stroma relative to tumour (n = 9) (CD68 +: p = 0.0117, PD-L1 + CD68 +: p = 0.0039, PD-L1 + FOXP3 + CD4 + p = 0.0039, paired samples Wilcoxon signed-rank test)." (PMID 34359755, 2021). "Therefore, distinct patterns of CD39 and CD103 expression describe tumor-reactive CTLs (CD8+/CD39+/CD103+) and tumor infiltrating Tregs (CD4+/CD39+/CD103−)." (PMID 34290905, 2021). "Furthermore, the DP EM/EMRA CD4+ and CD8+ T subsets in the tumor exhibited a significantly higher frequency of PD-1 and TIGIT-expressing T cells compared to DN T cells." (PMID 34386013, 2021). "The high levels of IL-12, GM-CSF, and IFN-γ in the TME strongly activated endogenous and exogenous DCs, which migrated to the draining lymph nodes and promoted the activation and infiltration of CD4+ and CD8+ T cells into the tumor, finally leading to robust tumor regression." (PMID 35111169, 2021). "Further, it is important to note that our lymphocyte culture has consistently resulted in a cell viability of greater than 95% through all five stimulation cycles for CD4+T cells obtained from DLNs, tumor splenocytes, non-tumor splenocytes and TILs." (PMID 33918403, 2021). "We observed an increased number of TAMs, neutrophils, and AMs, a low level of IFN-y, enhanced infiltration of CD4+ T cells, and a reduction in CD8+ cytotoxic T cells in non-tumor aneuploid areas of the lung implicating CIN in the development of an immunosuppressive environment." (PMID 34885137, 2021).